IL17A (interleukin 17A)
Diseases named in the same sentence as IL17A in open-access papers (continued):
Sharing a sentence is not in itself a finding about the gene and the disease.
Obesity (continued). "Likewise, in females with obesity, vaccinated mice had significantly lower levels of eotaxin, GM-CSF, GRO-α, IL-1β, IL-2, IL-5, IL-6, IL-12p70, IL-17A, IL-18, IP-10, MCP-1, MCP-3, MIP-1α, MIP-1β, MIP-2α, and TNF-α compared to unvaccinated controls." (PMID 41488663, 2025). "Intriguingly, HFD feeding in the absence of obesity did not modulate BLG-driven Th2 polarization but selectively elevated IL-17A production in antigen-restimulated MLN cells." (PMID 40509380, 2025). "Obesity increases the number of epidermal γδ T cells expressing CCR6 and IL-17A during wound healing, which underscores the significant impact of obesity on skewing toward an IL-17 proinflammatory response." (PMID 40073267, 2025). "Thus, increased IL-17A in CD11cΔLKB1 mice plays a central role in promoting liver steatosis and metabolic dysfunction during HFD-induced obesity." (PMID 37140993, 2023). "Meanwhile, it provides new insights into the role of IL-17A and IFN-γ in diet-induced obesity." (PMID 36781473, 2023). "Our findings also suggest that the effect of leptin on IL-17A production in CD4+ T cells is not influenced by obesity status." (PMID 35111163, 2021). "IL-17A is known to play a critical role in obesity and HIV infection, and inhibition of the IL-17A signaling pathway in adipocytes has been shown to attenuate diet-induced obesity in mice." (PMID 35111163, 2021). "Concomitantly, markers of endothelial dysfunction correlated with cytokines levels of the Th1 immune orientation (IFNγ, TNFα), inflammation (IL-17a, MIP1α, G-CSF, TNFα, MIP1β, and IFNγ), and/or M1 activation (IL-6, IFNγ, TNFα, IP10, MIP1α, and MCP1), mostly in patients with obesity." (PMID 34038475, 2021). "Furthermore, we observed that both the total duration and increased duration of light PA were negatively associated with the plasma levels of inflammatory cytokines/chemokines including IL-17A and MCP-1 which are known to be elevated in obesity." (PMID 32403230, 2020). "For ustekinumab and IL-17A agents, data examining the influence of obesity on the therapeutic efficacy are scare and even lacking in IJD." (PMID 32183053, 2020). "Unlike “classic” pro-inflammatory mediators, for example TNF-α, IL-6 and C-reactive protein, T cell-derived cytokines, such as IL-17A, have not been extensively investigated in obesity." (PMID 26263971, 2015). "In conclusion, our data indicate that pulmonary rather than systemic IL-17A is important for obesity-related AHR and suggest that changes in pulmonary Cfd expression contribute to these effects of IL-17A." (PMID 25309539, 2014). "The lack of correlation in our study indicates that IL-17A might not be involved in activating neutrophils in children with overweight/obesity." (PMID 39902293, 2024). "Obesity resulted in a marked increase in the expression of cyclooxygenase-2 (COX-2) and IL-6 in the adipose tissue of HFD animals, with concurrent moderate increases in TNF-α, IL-17A, and IL-18, while IL-1β changes were minor and inducible nitric oxide synthase (iNOS) expression was reduced." (PMID 38672413, 2024). "However, recently published studies with SEC, another IL17A inhibitor, show that neither obesity nor any other element of the metabolic syndrome (MetS) appears to negatively influence survival of this therapeutic class." (PMID 36675395, 2023). "Despite obesity dysregulates IL17-A production, and no data was found concerning its meaning in eutrophic patients, these findings support that pesticide exposure induce significant immunological changes in breast cancer patients, which vary according to the clinicopathological status of patients." (PMID 37942322, 2023). "Finally, lipocalin-2 (LCN2), an adipokine correlated with obesity and IR, has been shown to exacerbate psoriatic skin lesions in mice, through increase of IL-17A/F, IL-23p19, IL-12p40, CCL20 and TNF-α, levels, but not IL-12p35." (PMID 28708082, 2017).
Obesity (continued). "Obesity-induced NAFLD progression is associated with increased systemic and hepatic IL-17A expression, however whether IL-17 axis plays a role in other models of NAFLD has not been examined." (PMID 26895034, 2016). "In other systems, IL-17A synergizes with other cytokines including TNFα to promote changes in cell function and similar synergistic effects of TNFα and IL-17A may be necessary to drive AHR in obesity." (PMID 25309539, 2014). "This delay between the onset of obesity and the onset of AHR is consistent with previous observations in HFD fed mice, and may be the result of the time required for the induction of conditions necessary for recruitment of IL-17A+ cells to the lung." (PMID 25309539, 2014). "However, the absence of increases in serum IL-17A despite increases in AHR with HFD, in conjunction with the observations that obesity-related AHR does not occur in IL-17A-deficient mice, suggest that the source of the IL-17A that is important for AHR is the lung not the blood." (PMID 25309539, 2014). "Of the 13 cytokines measured, placental production of the pro-inflammatory cytokine IL-17A (P = 0.0361) was significantly increased in GDM non-obese compared to NGT non-obese, suggesting a dysregulation that is independent of obesity." (PMID 38334487, 2024). "Obesity did not alter the percentages of circulating IFNγ+ CD8 T cells or IFNγ+, IL-4+, or IL-17A+ CD4 T cells in ccRCC subjects." (PMID 32469992, 2020). "In an animal model of obesity, it has been reported that BAL and serum IL-17A levels were not affected by the type of diet." (PMID 32849611, 2020). "Data presented here extend those observations by showing that pulmonary rather than systemic IL-17A is important for obesity-related AHR and suggest that changes in pulmonary Cfd expression contribute to the AHR-promoting effects of IL-17A." (PMID 25309539, 2014).
breast cancer (295 papers, 2007 to 2026). A primary or metastatic malignant neoplasm involving the breast. "IL-17A gene polymorphisms have been linked to several malignancies, including gastric and breast cancer." (PMID 38438955, 2024). "The correlation between IL-17A gene rs3748067 variant and breast carcinoma was examined for the first time in 2012 by Wang and colleagues in Chinese Han women." (PMID 38816694, 2024). "High levels of IL-17A in the breast microenvironment are associated with the highly invasive and aggressive phenotype of breast cancer." (PMID 36835413, 2023). "The findings reveal that breast cancers cause γδ T cells to release IL-17A, which causes systemic proliferation and polarization of neutrophils to the CD8+ T cell suppressor type, followed by the establishment of breast tumour metastasis in distant organs." (PMID 37162544, 2023). "The expression levels of genes encoding downstream products of IL-17A/IL-17F signaling were downregulated in breast cancer with high ER expression." (PMID 33102239, 2020). "The consequence indicates that increased expression of IL-17A and IL-17F is associated with low levels of ER in breast cancer." (PMID 33102239, 2020). "On the other hand, the majority of genes encoding downstream products of IL-17A and IL-17F signaling transduction had increased expression levels in ER-negative and basal-like breast cancer." (PMID 33102239, 2020). "Genetic polymorphisms in IL-17F and IL-17A were reported to be significantly associated with susceptibility of breast cancer in human." (PMID 28101335, 2017). "Another study showed that three single nucleotide polymorphisms (SNPs) in the IL-17A gene are associated with increased breast cancer risk in a Chinese patient population." (PMID 26783383, 2015). "Several studies have revealed that IL-17A and IL-17F polymorphisms are associated with gastric cancer, breast cancer, and so on." (PMID 25147431, 2014). "Recently, IL-17A has emerged as a critical factor in enhancing breast cancer (BC)-associated metastases." (PMID 24674692, 2014). "The associations of IL-17A and IL-17F SNPs with breast cancer were further analyzed with the Haploview program." (PMID 22461912, 2012). "In conclusion, our study determined the relationships between IL-17A and IL-17F gene polymorphisms and the risk of breast cancer in Chinese women." (PMID 22461912, 2012). "Finally, the presence of IL17A can also be stimulated by fungal overgrowth, which has been linked to a reduced immune response in breast cancer and melanoma." (PMID 40831074, 2025). "IL-17A SNPs have been linked to several malignancies, including gastric and breast cancer." (PMID 38438955, 2024). "Since chemotherapy is the standard treatment in triple-negative early breast cancer, when considering the plausible cause of elevated IL-17A level during adjuvant treatment, it should be kept in mind that chemotherapy causes tissue injury that is commonly accompanied by inflammation." (PMID 37427128, 2023). "Previous research has shown that mutations in the IL-17F and IL-17A genes lead to inflammatory disorders such as inflammatory bowel disease, asthma, rheumatoid arthritis, ovarian carcinoma, and colon and breast cancer." (PMID 36134995, 2022). "IL-17A, a member of the unique IL-17 cytokine family, plays a causal role in tumor biology, including colorectal cancer, lung cancer, pancreatic cancer, and breast cancer." (PMID 36046049, 2022). "IL-17A polymorphisms have been linked to several malignancies, including gastric and breast cancer." (PMID 36134995, 2022). "Upregulation of IL-17A signaling is associated with increased expression of programmed cell death protein 1 (PD-1) and programmed death-ligand 1 (PD-L1) in breast cancer with low ER expression and may elevate the infiltration of CD8+ T cells in tumor tissue." (PMID 33102239, 2020).
breast cancer (continued). "Therefore, it is expected that genes related to the IL-17A/IL-17F signaling pathway increases immune infiltration in breast cancer tissues, especially genes that encode downstream products of IL-17A/IL-17F signaling transduction." (PMID 33102239, 2020). "Therefore, it is supposed that IL-17A is potentially associated with the upregulation of the PD-1/PD-L1 axis in breast cancers with low ER expression." (PMID 33102239, 2020). "IL-17A is a pro-inflammatory cytokine associated with poor prognosis in breast cancer." (PMID 27935862, 2017). "Previous studies indicated that mutations in IL-17F and IL-17A genes were related with inflammatory conditions e.g. inflammatory bowel disease, asthma, rheumatoid arthritis, ovarian cancer, colon cancer and breast cancer." (PMID 28101335, 2017). "Furthermore, the mutation of IL-17A rs2275913G>A locus was also demonstrated as tumorigenic for bladder cancer, breast cancer, and cervical cancer." (PMID 25147431, 2014). "Both IL-17A and IL-17F gene polymorphisms may provide valuable information for predicting the prognosis and effectiveness of pharmaceutical treatment in Chinese breast cancer patients." (PMID 22461912, 2012). "Our previous study suggested that SNPs in IL-17A were associated with the risk of breast cancer." (PMID 23239971, 2012). "In our case-control study, for the first time we investigated the associations between eight SNPs in the IL-17A (rs2275913, rs3819025 and rs3748067) and IL-17F (rs763780, rs7771511, rs12203582, rs9382084 and rs1266828) genes and the risk of sporadic breast cancer in Chinese Han women." (PMID 22461912, 2012). "From the analysis of clinical information in conjunction with IL-17A or IL-17F gene polymorphisms, we found that the IL-17A and IL-17F genes may influence the diagnosis, treatment, and prognosis of breast cancer." (PMID 22461912, 2012). "Both IL-17A and IL-17F gene polymorphisms may provide valuable information for predicting the prognosis of breast cancer in Chinese women." (PMID 22461912, 2012). "According to these results, the variants of IL-17A and IL-17F may be important in the prognosis of breast cancer and determining the effectiveness of pharmaceuticals treatments." (PMID 22461912, 2012). "Moreover, they reported the association of IL17A SNPs with the risk of breast cancer." (PMID 36556060, 2022). "The significant association between IL-17A and participants ethnicity could be attributed to several factors, remarkably, based on 2009–2010 cancer prevalence in Sudan, 37.8% of the total cancer patients were diagnosed with breast cancer." (PMID 32616024, 2020). "In breast cancer, higher expression of IL-17 is linked with greater probability for recurrence, greater chemotherapy resistance (to docetaxel), shorter disease free survival, and poor prognosis, which suggests that local IL-17A might be used to monitor disease progression and response to therapy." (PMID 28035060, 2017). "In addition, both PDL1 and IL-17A are associated with poor prognosis in breast cancer; thus, targeting of PDL1 and IL-17A might be an effective treatment for breast cancer." (PMID 27935862, 2017). "We genotyped three single-nucleotide polymorphisms (SNPs) in IL-17A (rs2275913, rs3819025 and rs3748067) and five SNPs in IL-17F (rs7771511, rs9382084, rs12203582, rs1266828 and rs763780) to determine the haplotypes in 491 women with breast cancer and 502 healthy individuals." (PMID 22461912, 2012). "However, it remains unknown whether genetic polymorphisms in IL-17A and IL-17F influence the risk of breast cancer development." (PMID 22461912, 2012). "Therefore, our investigation suggests that IL-17A, but not IL-17F, contributes to breast cancer susceptibility, and the Chinese women with these risk factors in the IL-17A gene may have an increased susceptibility to breast cancers." (PMID 22461912, 2012).
breast cancer (continued). "Therefore, the polymorphism in rs3748067 may change the IL-17A expression and further affect the prognosis of breast cancer patients." (PMID 22461912, 2012). "A study in a breast cancer model demonstrated that IL-17A-producing γδ T cells induced resistance to anti-PD-1 and anti-TIM-3 immune therapy." (PMID 39906741, 2024). "The progression of breast cancer is influenced by the production of γδ IL-17A, which is a key factor for various subtypes of γδ T cells." (PMID 39253082, 2024). "IL-17A upregulated CXCL1 secretion in breast cancer cells, resulting in the enhanced migration, invasion, and increased expression of pAKT and pNF-κB." (PMID 38255960, 2024). "Similar to IL-17A, IL-17B has been shown to accelerate breast cancer development by activating the ERK and NF-κB pathway and by enhancing the expression of anti-apoptotic Bcl-2 family members." (PMID 39906741, 2024). "For example, IL-17A, as a mediator of inflammation-related cancer, promotes the progression of several malignancies, including breast cancer, colorectal cancer, lung cancer, and CC." (PMID 38800011, 2024). "It has also been shown that IL-17A can directly promote the migration and angiogenic activity of breast cancer tumor cells and enhance anoikis resistance." (PMID 39906741, 2024). "Another study indicated that targeting IL-17A in a mouse model of breast cancer inhibited PD-L1 expression." (PMID 39906741, 2024). "Significantly higher serum IL-17A concentration in triple negative subtype was also recorded during adjuvant treatment after surgery compared to luminal A breast cancer." (PMID 37427128, 2023). "Significantly higher serum concentrations of IL-17A were found in women with early breast cancer before surgery, but also during adjuvant treatment in comparison to healthy controls." (PMID 37427128, 2023). "The results suggest that the immune response in early breast cancer is mediated by IL-17A, particularly in triple-negative breast cancer." (PMID 37427128, 2023). "In 2013 Cochaud and colleagues analyzed the role of IL-17A and IL-17A producing TILs in human breast cancers." (PMID 37427128, 2023). "As elaborated well above, IL-17A is potentially significant in the growth, proliferation, and progression of human cancer, including breast cancer." (PMID 36993955, 2023). "A statistically significant decrease in the level of IL-17A in the serum of women with early breast cancer was recorded during adjuvant treatment after surgery compared to the values before surgery." (PMID 37427128, 2023). "Taken together, these data show that genetic deletion of IL-17A–producing Vγ6+ and Vγ4+ cells sensitizes metastatic mammary cancer cells to checkpoint inhibitor immunotherapy." (PMID 36480166, 2023). "The role of IL-17A in cancer is controversial: while IL-17 activates antineoplastic cytotoxic T cells in melanoma and ovarian cancer, it also induces an immunosuppressive microenvironment in mammary tumors and breast cancer tissues." (PMID 35740551, 2022). "In blood samples and invasive ductal carcinoma (IDC) tissue collected from breast cancer patients, Th17-related molecules (IL-17A, RORC, and CCR6), produced by tumor-infiltrating CD4+ and CD8+ T lymphocytes, were observed to be upregulated." (PMID 35954312, 2022). "The systemic neutralization of IL-17A significantly reduces breast cancer metastasis in mice by reducing expression of CXCL12/SDF-1 in the metastatic niches." (PMID 33922795, 2021). "Coffelt’s research showed that, in a breast cancer mouse model, IL17A-producing γδ T cells induced neutrophil expansion and polarization, which created a premetastatic immunosuppressive microenvironment." (PMID 34721375, 2021). "IL-17A, a pro-inflammatory cytokine, has emerged as a critical factor in enhancing breast cancer metastasis." (PMID 33922795, 2021). "Previous studies have reported that ILs such as IL-17A, IL-22, and IL-33 promote neoplastic cell transformation and breast cancer tumorigenesis." (PMID 33800170, 2021).